CSKMT (citrate synthase lysine methyltransferase)
Description:
Protein-lysine methyltransferase that selectively trimethylates citrate synthase (CS) in mitochondria. Seems to conduct trimethylation in a highly distributive manner rather than in a processive manner, and thus introduces a single methyl group per binding event.
Synonyms: CS-KMT; METTL12; U99HG
Tractability: No criterion of Open Targets' tractability assessment is met for any kind of drug.
Gene: Protein-coding gene on chromosome 11 (62,665,309 to 62,668,496, forward strand). Ensembl gene ENSG00000214756.
Subcellular location: Mitochondrion
Pathways (Reactome):
Metabolism: Maturation of TCA enzymes and regulation of TCA cycle
Gene Ontology:
Molecular function: lysine N-methyltransferase activity; protein binding; protein-lysine N-methyltransferase activity
Biological process: peptidyl-lysine dimethylation; peptidyl-lysine monomethylation; peptidyl-lysine trimethylation; tricarboxylic acid cycle
Cellular component: mitochondrion; mitochondrial matrix
Genetic constraint (gnomAD): Loss-of-function variants: 16 observed, 12.1 expected, observed/expected ratio (o/e) 1.32, 90% interval 0.89 to 1.86. The upper end of that interval is the gene's LOEUF score, 1.86, which puts it in group 6 of 6, group 1 being the genes least tolerant of losing a copy. Missense variants: 328 observed, 311.51 expected, observed/expected ratio (o/e) 1.05, 90% interval 0.96 to 1.15. Synonymous variants: 142 observed, 135.35 expected, observed/expected ratio (o/e) 1.05, 90% interval 0.91 to 1.21.
Homologues: Orthologues: chimpanzee CSKMT (99% identical), macaque CSKMT (94% identical), pig CSKMT (84% identical), rabbit CSKMT (82% identical), dog CSKMT (78% identical), guinea pig CSKMT (75% identical), zebrafish cskmt (38% identical), Caenorhabditis elegans C52B9.8 (12% identical), Caenorhabditis elegans F52F12.9 (10% identical), Caenorhabditis elegans Y34B4A.7 (10% identical). Paralogues in human: METTL13 (24% identical), EEF1AKMT4 (22% identical).